MC4R (melanocortin 4 receptor)
Diseases named in the same sentence as MC4R in open-access papers (continued):
Sharing a sentence is not in itself a finding about the gene and the disease.
liver fibrosis (13 papers, 2013 to 2025). "In this study, the histological analysis revealed CLS formation and liver fibrosis (pericellular fibrosis) in Mc4r-deficient mice fed a WD, which was markedly suppressed by the Taxifolin treatment." (PMID 36678220, 2023). "A recent study reported that both FTP720 and JTE-013 induced inflammation and promoted liver fibrosis in a WD-fed melanocortin-4 receptor (Mc4r)-deficient NASH mouse model by inducing aberrant methylation." (PMID 34831031, 2021). "Taken together, these findings suggest that OCA effectively suppresses the formation of hCLS, thereby inhibiting chronic inflammation-induced liver fibrosis in MC4R-KO mice." (PMID 29802399, 2018). "In this study, histological analysis revealed that EPA treatment for 4 weeks significantly suppressed the progression of liver fibrosis in MC4R-KO mice." (PMID 25816330, 2015). "The patients with fibrosis stage 2 showed the highest number of hCLS, which is consistent with our observations that most of the MC4R-KO mice fed a WD for 20 weeks exhibited liver fibrosis corresponding to fibrosis stage 2 in the scoring system for human NASH." (PMID 24349208, 2013). "hCLS was also observed in the liver from wildtype mice fed a HFD for one year, at which they develop liver fibrosis comparable to MC4R-KO mice on a HFD for 20 weeks." (PMID 24349208, 2013). "CANA treatment for 20 weeks inhibited the development of hepatic fibrosis in WD-fed MC4R-KO mice." (PMID 29402900, 2018). "Accordingly, PFD significantly reduced liver fibrosis in WD-fed MC4R-KO mice." (PMID 28303974, 2017). "Longer treatment durations may be necessary to improve liver fibrosis in WD-fed MC4R-KO mice." (PMID 41266634, 2025). "In addition, we examined the effect of anagliptin treatment on cell death in the liver, because the score of ballooning degeneration is positively associated with the number of hCLS in human NASH and hepatocyte death triggers hCLS formation and liver fibrosis in MC4R-KO mice." (PMID 31969650, 2020). "Collectively, adipose tissue may contribute to the pathogenesis of liver fibrosis in MC4R-KO mice." (PMID 25816330, 2015). "Intriguingly, OCA markedly reduces hCLS formation even after MC4R-KO mice developed NASH, thereby inhibiting the progression to liver fibrosis." (PMID 29802399, 2018). "Intriguingly, treatment with OCA markedly reduced hCLS formation even after MC4R-KO mice developed NASH, thereby inhibiting the progression of liver fibrosis." (PMID 29802399, 2018). "Although the area of liver fibrosis was not increased in wildtype mice throughout the experimental period, MC4R-KO mice developed obvious liver fibrosis at 20 weeks of WD feeding (P<0.01)." (PMID 24349208, 2013). "Whereas CANA did not attenuate hepatic TG content in WD-fed MC4R-KO mice after treatment for 52 weeks, CANA significantly reduced liver fibrosis and serum ALT levels." (PMID 29402900, 2018).
Abdominal obesity (11 papers, 2012 to 2025). Excessive fat around the stomach and abdomen. "Our study shows a frequency of 2.52% of MC4R mutations leading to a reduced function in our sample of Spanish of children with abdominal obesity." (PMID 31035493, 2019). "Iranians consume a large amount of carbohydrate in their usual diets, which in case of being the carrier of MC4R rs17782313 risk allele, may be at higher risk for general and central obesity." (PMID 35538513, 2022). "Of the two abdominal obesity SNPs only MC4R rs17782313 was individually associated with MetS." (PMID 23101478, 2012). "The most common genetic variant of the FTO gene (rs9939609 A/T) and a variant near the MC4R gene (rs17782313 C/T) were detected recently and both single nucleotide polymorphisms (SNPs) have been associated mainly with overall and, in some cases, abdominal obesity." (PMID 23849767, 2013). "The MC4R rs12970134 association with BMI and the FTO rs8050136 association with central obesity appeared to be more pronounced with higher energy intake (β = 0.140 kg/m2, p = 0.049; OR = 1.77, p = 0.004, respectively)." (PMID 33668547, 2021). "Our aim was to screen for mutations in the MC4R and LCN2 genes in a Spanish pediatric population with abdominal obesity." (PMID 31035493, 2019). "In summary, MC4R and LCN2 mutations were detected in 2.42% and 0.84%, respectively, of Spanish children with abdominal obesity." (PMID 31035493, 2019). "Specifically, MC4R and LCN2 mutation carriers having abdominal obesity were able to reduce BMI-SDS after a lifestyle intervention." (PMID 31035493, 2019). "MC4R and LCN2 mutations were detected in 2.42% and 0.84%, respectively, of Spanish children with abdominal obesity." (PMID 31035493, 2019). "The results indicated that four SNPs (FTO rs9939609, MC4R rs17782313, GNPDA2 rs10938397, BDNF rs6265) and GRS calculated from these 4 SNPs significantly predicted the risk of central obesity." (PMID 23424664, 2013). "The joint effect of four strongly associated SNPs (FTO rs9939609, MC4R rs17782313, GNPDA2 rs10938397, BDNF rs6265) on the risk of central obesity was further investigated." (PMID 23424664, 2013). "In conclusion, our study confirmed the significant association of four SNPs (FTO rs9939609, MC4R rs17782313, GNPDA2 rs10938397, BDNF rs6265) with risk of central obesity in the Chinese children." (PMID 23424664, 2013). "Our study presents the new evidence that FTO rs9939609, MC4R rs17782313, GNPDA2 rs10938397 and BDNF rs6265 are statistically significantly associated with risk of central obesity in the Chinese children." (PMID 23424664, 2013). "Our study replicates the statistically significant association of four SNPs (FTO rs9939609, MC4R rs17782313, GNPDA2 rs10938397, BDNF rs6265) with risk of central obesity in the Chinese children." (PMID 23424664, 2013). "LEPR/GG average weight of 80.33 kg, BMI of 27.64, and WC of 88.49 cm, HC 103.48 cm, WHR 0.84 and MC4R/CC average weight of 82.65 kg, BMI 28.93, WC 82.10 cm, HC 99.87 cm, WHP at 0.81 indicate a trend towards higher body fat and central obesity." (PMID 39203789, 2024). "Thus, to precisely investigate and remove gender-specific associations, the present study was undertaken to assess the interactions of MC4R rs17782313 and dietary carbohydrate, GI, and GL on BMR and general and central obesity in overweight/obese women." (PMID 35538513, 2022). "A 12-year longitudinal study showed that FTO rs8050136 and GNPDA2 rs10938397 SNPs, rather than MC4R rs17782313, predicted persistent central obesity in the Chinese adults." (PMID 23424664, 2013).
polycystic ovary syndrome (10 papers, 2009 to 2025). A disorder that manifests as multiple cysts on the ovaries. "This study aimed to evaluate the association between selected gene polymorphisms (CYP19, INSR, FTO, MC4R) and polycystic ovary syndrome in a group of Polish women." (PMID 40725495, 2025). "We found that 13% (2/15) of women (age 16-50 years) with SRC-1 variants had a history of polycystic ovary syndrome (with hyperandrogenism and hirsutism); this was comparable to severely obese women with MC4R deficiency (9%; 2/22) of comparable BMI." (PMID 35137184, 2022). "A study in 2019 showed that MC4R rs17782313 was associated with obese polycystic ovary syndrome in the Western region of Saudi Arabia, and another study from Saudi Arabia showed rs17782313 to be associated with moderate obesity." (PMID 32733386, 2020). "The aim of this study was to assess the association between selected genetic polymorphisms (CYP19, MC4R, FTO, and INSR) and the clinical manifestations of polycystic ovary syndrome in Polish women." (PMID 40725495, 2025). "In this section, we analyze the relationship between the occurrence of selected clinical symptoms of polycystic ovary syndrome and the presence of specific genetic polymorphisms in the CYP19, INSR, MC4R and FTO genes." (PMID 40725495, 2025). "Overexpression of MC4R in the ARC region may link to metabolic disorders of induced polycystic ovary syndrome and energy balance stimulation in the rats." (PMID 38448811, 2024).
Glucose intolerance (9 papers, 2016 to 2024). Glucose intolerance (GI) can be defined as dysglycemia that comprises both prediabetes and diabetes. "Restoring expression of MC4Rs specifically in the lateral hypothalamic nucleus improves glucose intolerance in obese MC4R-null mice through bilateral interscapular brown adipose tissue denervation without affecting body weight or circulating insulin levels." (PMID 38448811, 2024). "Acute activation of the GABAergic AgRP-DMH circuit promoted food intake and glucose intolerance, while activation of post-synaptic MC4R neurons in the DMH elicited exactly opposite phenotypes." (PMID 37043384, 2023). "In the DIO MC4R KO mice, neither the monotherapies nor the combination of DMPP and icilin ameliorated glucose intolerance." (PMID 30353008, 2018).
Alzheimer disease (8 papers, 2013 to 2025). A progressive, neurodegenerative disease characterized by loss of function and death of nerve cells in several areas of the brain leading to loss of cognitive function such as memory and language. "In the brain, melanocortin receptor MC4R was shown to have important roles in the pathophysiology of various neurological disorders like Alzheimer's disease and cerebral ischemia." (PMID 40015967, 2025). "For instance, activating the hippocampal MC4R circuit alleviated synaptic plasticity impairments in Alzheimer's disease indicating that MC4R has therapeutic potential in conditions where synaptic function is compromised." (PMID 40015967, 2025). "In the CNS melanocortins have proven to be anti-inflammatory and neuroprotective peptides in models of brain ischemia and sepsis and to improve cognitive function, acting through MC4R, in a model of Alzheimer’s disease (AD) or after cytokine treatment." (PMID 27359332, 2016). "This suggests that the modulation of MC4R could potentially protect against neuronal damage in conditions such as ischemic stroke, traumatic brain injury, spinal cord injury, and Alzheimer’s disease." (PMID 41002740, 2025). "Furthermore, afamelanotide stimulates BDNF expression in the brain by activating MC4R to mediate neurogenesis and cognitive function in an Alzheimer’s disease animal model." (PMID 34836030, 2021). "On the contrary, several studies have reported that activation of MC4R obviously inhibited the overexpression of TNF-α, IL-6, and IL-1β in cerebral ischemia, Alzheimer’s disease, and subarachnoid hemorrhage." (PMID 29642894, 2018). "No Phase II or III clinical trials have yet evaluated MC4R agonists in multiple sclerosis, Alzheimer’s disease, or related conditions." (PMID 41002740, 2025).
Hypercholesterolemia (8 papers, 2014 to 2025). An increased concentration of cholesterol in the blood. "MC4R-KO mice exhibited hypercholesterolemia, whereas cholesterol accumulation and lysosomal stress were observed only in the CD11c-positive macrophages in CLS, suggesting that free cholesterol is derived from dead hepatocytes." (PMID 37725372, 2023). "Therefore, changes seen in Mc4r may participate in the exaggerated liver lipid content, and hypercholesterolemia produced in females by developmental exposure to L-DE-71." (PMID 36277707, 2022).
breast carcinoma (7 papers, 2013 to 2025). "In a Brazilian cohort of breast cancer patients and controls, the FTO SNPs rs1121980 and rs9939609, in combination with the melanocortin-4 receptor (MC4R) SNP rs17782313, were linked with an increased risk of breast cancer by 4.59-fold." (PMID 40361322, 2025). "In summary, we found that the FTO rs7185735 and MC4R rs476828 variants did not influence weight loss or improvement of metabolic parameters within the Mediterranean diet intervention in overweight or obese postmenopausal women with breast cancer receiving adjuvant hormone therapy." (PMID 35845810, 2022).
Cerebral ischemia (7 papers, 2013 to 2025). Restriction of arterial blood supply to the brain associated with insufficient oxygenation to support the metabolic requirements of the tissue. "In the context of cerebral ischemia, MC4R agonists counteract late inflammatory and apoptotic responses postischemia in a transient global brain ischemia model." (PMID 40015967, 2025). "Of great clinical importance is also the role of MC3R activation in preventing ventricular tachycardia and fibrillation in myocardial ischemia, as well as MC4R agonism for the treatment and recovery from cerebral ischemia." (PMID 34512392, 2021). "NDP-α-MSH was found to exert a strong neuroprotection, through the activation of MC4R, against damage following cerebral ischemia and traumatic brain injury." (PMID 23468969, 2013). "In addition, some studies have shown that the activation of MC3R and MC4R by their endogenous ligands is able to improve the outcome of cardiovascular diseases, such as myocardial and cerebral ischemia." (PMID 34512392, 2021). "The binding of MC4R to its endogenous ligand, α-melanocyte-stimulating hormone (α-MSH), has demonstrated the protective, anti-inflammatory, and anti-apoptotic effects in experimental renal ischemia/reperfusion, cerebral ischemia, and traumatic brain injury." (PMID 29642894, 2018). "The melanocortin 4 receptor (MC4R) is a seven-transmembrane G-protein–coupled receptor that could be activated by neuropeptide α-MSH, which exerts anti-inflammatory and neuroprotective effects after traumatic brain injury and cerebral ischemia." (PMID 32317935, 2020).
coronary artery disease (7 papers, 2019 to 2025). "They reported that the MC4R gene SNPs were associated with coronary artery disease (p < 5 × 10− 8)." (PMID 32807123, 2020). "For coronary artery disease, the OR (95% CI) per kg/m2 genetically lower BMI, was 0.94 (0.93–0.95) for the 97-variant polygenic score versus 0.82 (0.72–0.95) for the β-arrestin-biased MC4R GoF variants, Pheterogeneity = 0.07." (PMID 31002796, 2019). "However, the authors reported that there were no expression quantitative trait loci (eQTL) data or ENCODE features that indicated MC4R as the causal gene underlying the coronary artery disease susceptibility, which is in line with the null findings in our present study." (PMID 33804309, 2021).
eating disorder (7 papers, 2012 to 2025). A broad group of psychological disorders with abnormal eating behaviors leading to physiological effects from overeating or insufficient food intake. "It was found that in a sample of severely obese study participants, all those carrying gene mutations of the melanocortin 4 receptor (MC4R) gene met DSM-IV criteria for an eating disorder (BED)." (PMID 33807560, 2021). "The present findings add relevant preclinical information regarding the relevance of MC4-R signaling into the NAc as a potential target for therapeutic interventions for eating disorders and alcohol use disorders (AUDs) in humans." (PMID 28936166, 2017). "Continued investigation into the neural circuits and functional roles of the melanocortin–MC4R system in the ventral striatum will advance our understanding of feeding-related motivated behaviors and support the development of targeted interventions for eating disorders." (PMID 41262475, 2025).
LEPR deficiency (7 papers, 2020 to 2025). "The relative inability to learn and remember new things was variable in affected children but was more evident in children with LEP or LEPR deficiency (77% and 72%, respectively) as compared with those of children with MC4R deficiency (25%)." (PMID 37659411, 2023). "Serum levels of MDA and 8-OHdG were significantly higher and of GSH lower in individuals with LEP or LEPR deficiency compared with those with MC4R deficiency (p < 0.05)." (PMID 37659411, 2023). "Overall, only a small percentage of the children with LEP deficiency (22%) or with LEPR deficiency (27%) over the age of 5 years were reported to be attending school compared with 75% of children with MC4R deficiency." (PMID 37659411, 2023). "The treatments include hormone replacement therapy with recombinant leptin for subjects with LEP deficiency, the MC4R agonist setmelanotide for LEPR deficiency, and glucagon-like peptide-1 receptor agonists for subjects with MC4R deficiency." (PMID 37659411, 2023). "In summary, comparative data from this retrospective cross-sectional study indicate a distinctly higher level of morbidity in children with LEP or LEPR deficiency compared with those with homozygous loss-of-function mutations in the MC4R gene." (PMID 37659411, 2023). "This is also evidenced by the observation that only ∼25% of children with LEP or LEPR deficiency could attend school after the age of 5 years compared with 75% of children with MC4R deficiency." (PMID 37659411, 2023). "Targeted agonism of the MC4R with setmelanotide showed ~10% body weight loss in patients with POMC deficiency and LEPR deficiency, and there are case reports showing weight loss after GLP-1 therapy in individuals with pathogenic variants of MC4R." (PMID 38974580, 2024). "For patients aged 6 years and older with POMC deficiency, PCSK1 deficiency, LEPR deficiency, or BBS, MC4R agonists are approved which could be considered when available and reimbursed." (PMID 39929239, 2025). "The MC4R agonist, setmelanotide, should be administered in patients with POMC, PCSK1, or LEPR deficiency and BBS, and the GLP-1 receptor agonists, semaglutide and liraglutide are also novel pharmacological agents that have been FDA approved for the treatment of childhood obesity." (PMID 38397265, 2024). "Hypercortisolemia was more prominent in children with LEP deficiency compared with that in patients with LEPR deficiency, whereas cortisol levels were in the healthy range in patients with MC4R deficiency and were indistinguishable from those of the lean controls, as previously reported." (PMID 37659411, 2023).
melanoma (7 papers, 2013 to 2025). A malignant, usually aggressive tumor composed of atypical, neoplastic melanocytes. "In particular, the C allele in the rs17782313 SNP (within the melanocortin-4 receptor) was associated with increased BMI and poorer overall and melanoma-specific survival among patients with stage I/II melanoma, showing a trend towards the association with elevated CRP." (PMID 34631264, 2021). "As previously noted in glioblastoma and melanoma cells, pro-survival pathways in these tumor types are activated in part by MC4R signaling, and its pharmaceutical anticancer efficacy is correlated with the activation of ERK1/2." (PMID 40004697, 2025). "Additionally, obese MC4R−/− (melanocortin receptor 4 knockout) mice with high plasma leptin levels showed higher development of melanoma compared to lean controls." (PMID 24202338, 2013). "Furthermore, our research group has recently discovered the expression and important role of MC4R in melanoma human cells, but its role in other cancer types has not been explored yet." (PMID 40004697, 2025). "However, we could exclude the probable involvement of MC4R and MC5R, which are also present in B16-F10 melanoma cells." (PMID 31968661, 2020). "In our study, ML administration in vitro also blocked the ERK 1/2 pathway in a time- and concentration-dependent manner in A-2058 melanoma cells, whereas the inhibition of ERK 1/2 phosphorylation completely disappeared in A-2058 cells with no MC4R expression." (PMID 40004697, 2025). "Of note, EPAC rather than PKA inhibition abrogated CRE activation via MC1R in melanoma cells, supporting the hypothesis that the role of EPAC for melanocortin-induced gene expression is not restricted to the MC4R subtype." (PMID 27612207, 2016).